IGF1R (insulin like growth factor 1 receptor)
Diseases named in the same sentence as IGF1R in open-access papers (continued):
Sharing a sentence is not in itself a finding about the gene and the disease.
type 2 diabetes (37 papers, 2009 to 2025). "Further, there were also records associated with glucose metabolism (type 2 diabetes, positive regulation of glucose metabolic process, signaling of insulin via INSR, IGF1R, PKB, Pi3K, and MAPK)." (PMID 33445738, 2021). "Our present results suggest that haploinsufficiency of IGF-1R increases the probability for developing type 2 diabetes by diminishing peripheral insulin action and by preventing glucose stimulated compensatory increase in insulin secretion." (PMID 22132081, 2011). "For seven of overall 17 potential target genes, we found studies reporting a role in CVD, comprising HF and cardiac remodeling after MI (Ccnd2, Pde1c, Ddah1), atherosclerosis (Igf1r), blood pressure and hypertension (Fign, Efnb3), and type 2 diabetes (Igf2bp2)." (PMID 35332188, 2022). "Notably, several age-downregulated genes, such as Plxdc2, Igf1, Igf2bp3, and Igf1r, and upregulated genes, such as Adam19 and Tmem163, have been linked to IGF signaling or type 2 diabetes." (PMID 30180872, 2018). "Thus, deletion of muscle IGF-1R is sufficient to elicit type 2 diabetes, whereas low liver production of IGF-1 is also associated with type 2 diabetes, but responsible intracellular routes are unknown." (PMID 39638246, 2024). "Similarly, the NCT04767750 trial has been completed, with the objective of exploring the role of lncRNA H19 in the regulation of IGF-1R expression and investigating the mechanistic links between HCC and type 2 diabetes mellitus (T2DM)." (PMID 39827195, 2025). "FOS, IGF1R, IGF2, FOXO1, and NTF3 might target “TGF-β signaling pathway”, “the hedgehog signaling pathway”, “retinol metabolism”, or “type II diabetes mellitus” pathways respectively." (PMID 32694937, 2020). "To test this idea and investigate whether the membrane content of DGC is influenced by the fall in PI3K-Akt signaling, we used transgenic mouse (MKR) model for type 2 diabetes, which express a kinase-inactive form of IGF-1 receptor (IGF-1R) specifically in skeletal muscle." (PMID 32170063, 2020). "Based on the ceRNA network, we also discovered that FOS, IGF1R, IGF2, FOXO1, and NTF3 might target the “TGF-β signaling pathway”, “the hedgehog signaling pathway”, “retinol metabolism”, or “type II diabetes mellitus” pathways respectively, thereby modulating the subsequent development of ICC." (PMID 32694937, 2020). "Interestingly, IGF-1R expression in PTC appears to be higher in patients with type 2 diabetes mellitus (T2DM) than in non-diabetic patients." (PMID 29184536, 2017). "As far as we know, two previous studies in humans, with small sample size (n = 39–40), examined protein or gene expression of the IGF1, IGF2, IGFBP3, INSR, IGF1R and downstream targets IRS1, IRS2 and mTOR in women with or without type 2 diabetes." (PMID 29486734, 2018).
liver cancer (35 papers, 2008 to 2025). An epithelial or non-epithelial malignant neoplasm that arises from the liver. "Elevation in the activation of IGF/IGF-1R signaling in patients with liver cancer caused by hepatitis B infection has been widely reported." (PMID 33669204, 2021). "•IR loss reduces hepatic cancer burden; IGF1R loss increases liver tumor malignancy." (PMID 40115165, 2025). "Furthermore, the combined loss of IR and IGF1R signaling in PTEN-deficient livers restrains liver carcinogenesis, but both receptors have individually distinct effects on the malignancy of liver cancers, with IR deficiency reducing overall cancer incidence and IGF1R deficiency promoting malignancy." (PMID 40115165, 2025). "This study underscores the pivotal roles of phosphatase and tensin homolog (PTEN), insulin receptor (IR), and IGF-1 receptor (IGF1R) in controlling liver metabolism, systemic adiposity, and liver cancer progression." (PMID 40115165, 2025). "Similar results were obtained from knockdown experiments in another liver cancer cell line, HuH7, indicating that E-Syt1 contributes to the activation of IGF1R-Erk1/2 signaling in GPC3-positive liver cancer cells." (PMID 37241771, 2023). "For example, IGF/IGF-1R signaling pathway directly mediated cell proliferation and survival, and IGF-1R is often overexpressed in liver cancer tissues." (PMID 36698167, 2023). "Previous studies have also shown that extracellular PKCδ activates IGF1R signaling involved in GPC3-expressing liver cancer cell lines such as HepG2 and HuH7." (PMID 37241771, 2023). "Together, these findings demonstrate the role cytokines play in promoting liver cancer stemness through IGF/IGF-1R signaling." (PMID 33669204, 2021). "We take lung and liver cancer stem cells as an example to explain our concept of niche-specific effect on IGF-1R-mediated cancer stemness." (PMID 33511137, 2020). "It has been shown that knockdown of IGF-1R enhances chemo-sensitivity of many types of cancers, such as liver cancer cells." (PMID 24970814, 2014). "In addition, this research reveals the potential of IR and IGF1R as biomarkers in liver cancer development, presenting new opportunities for therapeutic targeting and disease monitoring." (PMID 40115165, 2025). "Furthermore, it has been reported to interact with glypican 3 (GPC3) in liver cancer cells, leading to activation of insulin-like growth factor 1 receptor (IGF1R) signaling, which is involved in tumorigenesis." (PMID 37241771, 2023). "Notably, extracellular PKCδ may have functions such as promoting growth of liver cancer cells by activation of the IGF‐1 receptor (IGF1R) and ERK1/2 signaling pathways." (PMID 38938161, 2024). "Furthermore, levels of p-ERK, VEGF, and HIF-α were reduced by curcumin in liver cancer cells the same way they were reduced in IGF-1R-knockout liver cancer cells, suggesting that curcumin suppresses tumour progression in an IGF-1R-dependent manner involving the MAPK pathway." (PMID 34867402, 2021). "Therefore, abnormal upregulation of IGF1R and HIF1A could promote the occurrence and metastasis of HBV-associated liver cancer." (PMID 33863948, 2021). "Therefore, the high expression of IGF-1R and EMT markers in sorafenib-resistant cells compared with naïve cells in the currently study has reinforced the evidence regarding the association of these genes with malignancy in liver cancer." (PMID 34359714, 2021). "In liver cancer, curcumin decreased VEGF, PI3K, and Akt expression, with one study suggesting that this effect is mediated via curcumin-inhibition of IGF-1R to suppress angiogenesis." (PMID 34867402, 2021). "Molecular studies have demonstrated that miR‐505 can target IGF‐1R and inhibit its expression, resulting in the suppression of the AKT/GLUT1 channel and glycolysis of liver cancer cells." (PMID 32348630, 2020). "To further identify how GSTZ1‐1 mediates IGF1R in hepatocarcinogenesis in vivo, we used the DEN/CCl4‐induced mouse model of liver cancer." (PMID 31267557, 2019).
liver cancer (continued). "We recently reported that EGCG inhibits the activation of IGF-1R in SW837 human colon cancer and HepG2 human liver cancer cells that display a constitutive activation of this receptor." (PMID 19325845, 2008). "Insulin-like growth factor-1 receptor (IGF-1R) is a receptor tyrosine kinase that plays a key role in abnormal cell growth, tumor invasion, and metastasis and is involved in the development of breast, colorectal, lung, and liver cancers." (PMID 37765064, 2023). "Nevertheless, direct evidence for IGF/IGF-1R signaling regulating liver cancer stemness through YAP activity has not yet been reported." (PMID 33669204, 2021). "Simultaneous targeting of IGF1R and mTOR by co-transfecting two miRNAs yields promising results for eradicating HCC cells, which could be a new direction for liver cancer treatment." (PMID 28624790, 2017). "On the basis of miR‐378a enhancing the sensitivity of liver cancer to sorafenib by targeting VEGFR, PDGFRβ and c‐Raf31, we further confirmed that the expression of miR-378a-3p was decreased in sorafenib-resistant HCC cells and identified IGF1R as the target gene of miR-378a-3p." (PMID 32754282, 2020).
cardiac hypertrophy (31 papers, 2009 to 2025). "Studies after si-IGF1R silencing in H9C2 cells revealed that IGF1R-pAKT1-pS6K1 signaling axis could be a mechanistic link between ABCB7 downregulation associated with cardiac hypertrophy and impaired mitochondrial function." (PMID 31511561, 2019). "Specifically, markers of non-cardiac differentiation, such as those for vascular endothelium (VWF) and non-cardiac muscle (CDH6, CNN2 and MYLK) were downregulated, while genes encoding for cardiac hypertrophy (IGF1R) and calcium handling (CAMK2B) were upregulated." (PMID 26785135, 2016). "The first was a model of physiological cardiac hypertrophy driven by overexpression of the IGF1R (IGF1R Tg mice)." (PMID 39018488, 2024). "Multiple intracellular signaling pathways participate in cardiac hypertrophy, including the IGF1R/PI3K/AKT, EGFR/MAPK, GP130/Jak/STAT3 and calcineurin/NFAT pathways." (PMID 35855640, 2023). "In support of this notion, mice with cardiomyocyte-specific overexpression of human IGF1R exhibit increased cardiac muscle mass and superior function, a phenotype often described to be reminiscent of exercise-induced myocardial hypertrophy in athletes." (PMID 35786404, 2022). "Mechanistically, the Ang II-induced upregulation of LMP10 inhibited the activation of autophagy, which in turn increased the stability of IGF1R and gp130 and subsequent development of cardiac hypertrophy." (PMID 32581853, 2020). "Numerous intracellular signalling pathways participate in cardiac hypertrophy accompanied by increased protein synthesis, such as IGF1R/PI3K/AKT, EGFR/ MAPKs, gp130/Jak/STAT3 and calcineurin/NFAT." (PMID 32343488, 2020). "To explore the molecular mechanism by which LMP10 KO attenuates Ang II-induced cardiac hypertrophy, we examined a range of prohypertrophic signaling pathways, including IGF1R, gp130, EGFR, and calcineurin A, and their downstream mediators." (PMID 32581853, 2020). "Mechanistically, LMP10 deficiency activated autophagy, which promoted the degradation of IGF1R and gp130, thereby inhibiting cardiac hypertrophy." (PMID 32581853, 2020). "They showed that activation of prohypertrophic insulin-like growth factor 1 receptor (IGF1R)-mediated PI3K/AKT signaling contributes to cardiac hypertrophy inBSCL2–/– mice." (PMID 31656583, 2019). "To investigate the significance of ABCB7 silencing mediated IGF1R signaling axis in cardiac hypertrophy or mitochondrial dynamics, we silenced the IGF1R gene in H9C2 cells transfected with either siRNA or siABCB7." (PMID 31511561, 2019). "We extracted an insulin-like growth factor 1 receptor-related subnetwork in cardiac hypertrophy and a vascular endothelial growth factor A-related subnetwork in AMI." (PMID 30514363, 2018). "Here, we suggested that IGF1R influenced cardiac hypertrophy through the FOXO signaling pathway by interacting with a series of miRNAs." (PMID 30514363, 2018). "We also extracted an insulin-like growth factor 1 receptor-related subnetwork in cardiac hypertrophy and a vascular endothelial growth factor A-related subnetwork in AMI." (PMID 30514363, 2018). "Overexpression of this miRNA attenuated cardiac hypertrophy and suppressed IGF‐1R expression in analogous way to the effects of miR‐322‐5p in response to MCT." (PMID 29511611, 2018). "Among them, the insulin growth factor 1 receptor (IGF1R)-phosphatidylinositol 3-kinase (PI3K)–protein kinase B (AKT)-mammalian target of rapamycin (mTOR) axis is considered as one of the most important signaling cascades governing adaptive cardiac hypertrophy." (PMID 34208388, 2021). "During hypertrophic stress, increased C/EBPβ downregulates the mir15a/mir16‐1 cluster, resulting in up‐regulation of multiple target proteins (INSR, IGF1R, AKT3, SGK1) in cardiomyocytes, causing increased activation of insulin/IGF1 signaling, ultimately causing cardiac hypertrophy and dysfunction." (PMID 33377640, 2020).
cardiac hypertrophy (continued). "Interestingly, IGF1R and gp130 are activated in hypertrophic hearts and contribute to the initiation of cardiac hypertrophy and heart failure as a response to pathological hypertrophic stress." (PMID 32581853, 2020). "We inferred that ATL1101 influenced cardiac hypertrophy via IGF1R and some essential miRNAs." (PMID 30514363, 2018). "Finally, we considered insulin-like growth factor 1 receptor and vascular endothelial growth factor A as two candidate drug targets by utilizing the cardiac hypertrophy and AMI pathways." (PMID 30514363, 2018). "miR-181b-5p had the most target genes for the IGF1R-centered subnetwork for cardiac hypertrophy." (PMID 30514363, 2018). "In the cardiac hypertrophy network, IGF1R was a target of ATL1101 and 19 other miRNAs." (PMID 30514363, 2018). "The IGF-1R signaling pathway has been reported to regulate cardiac hypertrophy via PI3K/Akt." (PMID 29440459, 2018). "Insulin-related pathways (cluster I) are also associated with the susceptibility to cause physiologic cardiac hypertrophy by over-expression of insulin-like growth factor 1 (IGF-1) and insulin-like growth factor 1 receptor (IGF1R), via the PI3K (p110alpha) pathway." (PMID 24751578, 2014). "Finally, the investigators transfected the HG-exposed cardiomyocytes with custom-synthesized miR-133a mimics and observed the attenuation of hypertrophy along with downregulation of SGK1 and IGF1R mRNAs, the targets of miR-133a in cardiac hypertrophy." (PMID 24528626, 2014). "Furthermore, the expression of IGF-1R was related to the expression of cell cycle regulatory molecules cyclins B, D1, D3 and E, and with echocardiographic measures of myocardial hypertrophy." (PMID 19818143, 2009). "Likewise, overexpression of IGF1R in heart induces cardiac hypertrophy." (PMID 36548088, 2023). "Thus, the effect of PPP to decrease body growth (serving as a positive internal control for IGF-1R inhibition) was comparable to the reduction in compensatory kidney hypertrophy, consistent with body weight gain and compensatory kidney hypertrophy both being driven in part via the IGF-1R." (PMID 34599260, 2021). "Taken together, these data suggest INSR, IGF1R, AKT3 and SGK1 are novel target genes contributing to mir15a/mir16‐1 inhibition‐mediated cardiac hypertrophy." (PMID 33377640, 2020). "Most recently, our lab observed that Tsg101 promoted the endosomal-mediated transport of the insulin-like growth factor-1 receptor (IGF-1R) to the plasma membrane (sarcolemma) of cardiomyocytes, leading to physiological cardiac hypertrophy." (PMID 32839388, 2020). "It is well reported that IGF1R and gp130 mediate three major downstream pathways, JAK/STAT, Ras/MEK/ERK, and PI3K/AKT, which play different roles in myocardial infarction, cardiac hypertrophy, and heart failure." (PMID 32581853, 2020). "The study elucidated the effect of miR-133a on HG-cardiac hypertrophy by downregulating SGK1 and IGF1R mRNAs." (PMID 24528626, 2014). "miR-145-5p is an important regulator of cardiac hypertrophy, in contrast, miR-145-5p is a well-established inhibitor of cardiac hypertrophy, suppressing pro-hypertrophic pathways by targeting genes such as GATA6 and IGF1R." (PMID 40874024, 2025). "The insulin-like growth factor 1 receptor (IGF1R)-phosphoinositide 3-kinase (PI3K) signalling pathway has been shown to play a critical role in regulating physiological postnatal cardiac growth and exercise-induced cardiac hypertrophy in adult mice." (PMID 39018488, 2024). "Conversely, concentric cardiac hypertrophy with preserved or enhanced systolic function and lack of fibrosis was found in mice overexpressing IGF1R or a constitutively active form of PI3K and AKT in cardiomyocytes." (PMID 34208388, 2021).
cardiac hypertrophy (continued). "In cardiac hypertrophy, the drug that participated in most of the dysregulated MGDTs was ATL1101, which is a second-generation antisense drug designed to block the synthesis of the IGF-1 receptor (IGF1R), a protein involved in the regulation of cell overgrowth in psoriasis." (PMID 30514363, 2018). "miR-139-5p also inhibits the expression of IGF-1R in cells both under basal and ISO-stimulated conditions, indicating that the down-regulation of IGF-1R and inhibition of Akt might be involved in preventing cardiac hypertrophy." (PMID 29440459, 2018).